RNU6-718P (RNA, U6 small nuclear 718, pseudogene)
Gene: Small nuclear RNA gene on chromosome 5 (120,337,549 to 120,337,653, reverse strand). Ensembl gene ENSG00000251975.
Homologues: Orthologues: chimpanzee U6 (96% identical), dog U6 (72% identical), dog U6 (70% identical), rabbit U6 (65% identical), dog U6 (63% identical), mouse Gm56092 (57% identical). Paralogues in human: RNU6-1158P (79% identical), RNU6-166P (79% identical), RNU6-252P (79% identical), RNU6-38P (79% identical), RNU6-456P (79% identical), RNU6-1011P (78% identical), RNU6-1145P (78% identical), RNU6-338P (78% identical), RNU6-476P (78% identical), RNU6-971P (78% identical), RNU6-1042P (77% identical), RNU6-116P (77% identical), and 1286 more.